HMGB1 (high mobility group box 1)
Diseases named in the same sentence as HMGB1 in open-access papers (continued):
Sharing a sentence is not in itself a finding about the gene and the disease.
colon carcinoma (continued). "This further confirmed that glucose deprivation in the presence of oxygen was a strong stimulant for HT-29 colon cancer cells to release HMGB1." (PMID 26979829, 2016). "Tumor cells overexpressing HMGB1 have been reported to secrete it to the extracellular matrix in erythroleukemia, neuroblastoma and colon cancer cells." (PMID 27391431, 2016). "Lastly, phosphorylation of serines 35, 53, and 181 by PKC-ζ has been described to enhance HMGB1 secretion in HCT116 colon cancer cells." (PMID 24928512, 2014). "Although some cancer cells have the ability to secrete HMGB1 into the culture media, these are limited and include colon cancer and malignant mesothelioma." (PMID 25512109, 2014). "In another study, anti-HMGB1 was shown to inhibit HMGB1-enforced angiogenic process of colon cancer cells." (PMID 23766911, 2013). "Although HMGB1 overexpression has been reported in colon cancer by the percentage over 90%, the serum level of HMGB1 and its clinical significance have not been reported." (PMID 22496788, 2012). "High mobility group box 1 protein (HMGB1), a nuclear protein, can be translocated to the cytoplasm and secreted in colon cancer cells." (PMID 22496788, 2012). "For this purpose, we have screened the expression and secretion of HMGB1 in 10 colon cancer cell lines and 1 control cell line and found that HMGB1 was detected in the culture medium." (PMID 22496788, 2012). "To identify HMGB1 secretion in colon cancer cells, we measured HMGB1 secretion in several colon cancer cells and compared the levels to those in normal cell line (CCD18Co) by western blot analysis." (PMID 22496788, 2012). "The HMGB1 form released by autophagic cells promotes cancer cell survival by limiting apoptosis in HCT116 human colon cancer cells, revealing the alter ego aspect of HMGB1 in immunogenic impact of cancer cells death." (PMID 24710486, 2012). "Our observations are compatible with a recent study reporting in human colon carcinomas a correlation between increased HMGB1 levels and enhanced amounts of c-IAP2." (PMID 20419158, 2010). "Correspondingly, HMGB1 protein levels were significantly elevated in 90% of the 60 colon carcinomas tested compared with corresponding normal tissues evaluable from the same patients." (PMID 20579387, 2010). "In colon cancer cells, the co-expression pattern of HMGB1 in the nucleus and cytoplasm was observed in a subset of cancer cells, whereas nuclear-only expression of HMGB1 existed in most colon cancer cells." (PMID 20846416, 2010). "For example, in colon cancer cell lines, E-selectin downregulated the cellular expression of HMGB1 but enhanced the release of HMGB1 into the culture medium." (PMID 20846416, 2010). "This study observed that the co-expression of nuclear and cytoplasmic HMGB1 was inversely associated with the infiltration of CD45RO+ cells and the 5-year survival rate in patients with stage IIIB colon cancer." (PMID 20846416, 2010). "Previous studies have shown that the co-expression of RAGE and HMGB1 led to enhanced migration and invasion by colon cancer cell lines." (PMID 20846416, 2010). "One possibility is that HMGB1 secreted by colon cancers promotes the angiogenesis switch and increases cancer cell invasiveness." (PMID 20846416, 2010). "Its upregulation in colon cancer cells inhibits proliferation and migration by targeting HMGB1." (PMID 39759512, 2024). "HMGB1 influences the relationship between the intestinal microbiome, mucosal epithelium, and mucosal immunity in both UC and sporadic colon cancer, and may promote the exacerbation of UC and carcinogenesis." (PMID 38999957, 2024). "Furthermore, upregulation of HMGB1, a multifunctional cytokine secreted by cancer cells, is associated with lymph node metastasis, suggesting that nodal DCs are suppressed by HMGB1 produced by colon cancer cells." (PMID 39119332, 2024).
colon carcinoma (continued). "In this study, we analyzed the effects of HMGB1 on mucosal immunity in the colon using mouse AOM carcinogenesis models, mouse DSS carcinogenesis models, human UC and UC-associated CRC samples, and samples of mucosa surrounding human colon cancer." (PMID 38999957, 2024). "In this study, we investigated the impact of genetic variation in TLR1 and TLR2, which are the receptors for HMGB1, on the clinical outcomes of colon carcinoma (COAD) patients who underwent postoperative adjuvant chemotherapy, specifically those with regional lymph node metastatic COAD." (PMID 37945630, 2023). "Overall, our results suggest that dysfunctional TLR1 may reduce the therapeutic response to adjuvant chemotherapy by impairing HMGB1-mediated DC maturation and attenuating the antitumor immune response in locally advanced colon carcinoma patients." (PMID 37945630, 2023). "Based on our results, we inferred that liposomal berberine could be an ICD inducer; thus, we assessed the release of other DAMPs (including extracellular ATP and HMGB1 protein) in colon cancer cells." (PMID 38275991, 2023). "However, the total protein levels of HMGB1 were significantly higher for both ovarian cancer and colon cancer." (PMID 35765707, 2022). "According to the colon cancer Cox regression test and Kaplan–Meier (K-M) curves of key genetic risk factors, the five most significant genes selected were: ELAV-like RNA-binding protein 1 (ELAVL1), GPX2, EPAS1, SLC7A5, and high mobility group box 1 (HMGB1)." (PMID 36324584, 2022). "Thus, HMGB1 is a promising therapeutic target in many malignancies such as prostate and colon cancer, and epidermal tumors." (PMID 36042902, 2022). "Specifically, these shared pathways with IBD were linked to inflammation (TNF, IL-1A, IL-1B, NFkB, IL-6) and growth (TREM1, TGFB1), while other pathways shared with colon cancer were associated with colorectal metastatic signaling, growth (TREM1, NFkB and HMGB1) and inflammation (IL-8, IL-6)." (PMID 35323693, 2022). "ERK/MAPK pathway is upregulated by HMGB1 in colon carcinoma." (PMID 34194625, 2021). "Serum HMGB1 of colon cancer patients was significantly higher than that of healthy subjects." (PMID 34867338, 2021). "In colon cancer, HMGB1 and its receptor, are indicators of progression." (PMID 34194625, 2021). "In addition, HMGB1 upregulation has been observed in breast cancer, colon cancer and gastrointestinal stromal tumor tissues." (PMID 34267603, 2021). "HMGB1 originated from PLTs‐activated neutrophils to release extracellular traps in colon cancer." (PMID 34288521, 2021). "Additionally, co-localization of HMGB1 in both the nucleus and the cytoplasm has been detected in colon cancer." (PMID 35201494, 2021). "HMGB1 promotes the proliferation, invasion, and metastasis of colon cancer cells." (PMID 34867338, 2021). "Studies have shown that HMGB1 is elevated in both sera and tumor tissues of colon cancer patients." (PMID 34867338, 2021). "Yet, the link between HMGB1 and inflammation in colon cancer remains unclear, and then we have proposed the hypothesis that HMGB1 mediated the inflammation in colon cancer." (PMID 32514250, 2020). "We report that HMGB1 mediates lipopolysaccharide (LPS)-induced inflammation in colon cancer cells." (PMID 32514250, 2020). "Another study showed that OXA, but not CDDP could trigger eco-CALR exposure using murine and human colon cancer cell lines, although both compounds resulted in HMGB1 release at similar levels." (PMID 32560232, 2020). "As result, based on these data, HMGB1 might play an antiapoptotic role in colon cancer and decrease anticancer immune responses by stimulated apoptosis in immune cells." (PMID 33117687, 2020). "Subsequently, by using of cancer and adjacent tissue from seven patients with colon cancer, we found that acetylated HMGB1 and p-P65 expression were increased, the results further demonstrated acetylated HMGB1 and p-P65 expression mediate inflammation in colon cancer." (PMID 32514250, 2020).
colon carcinoma (continued). "An example of ligand-dependent RAGE signaling was in colon cancer cells where AGEs increased cell migration and invasion predominantly through increased activities of iNOS and NF-κB, whereas in the same cells, HMGB1 acted mainly through activation of ERK1/2, Rac1, and Akt." (PMID 33086527, 2020). "Here we report that HMGB1 mediates LPS-induced inflammation in colon cancer cells." (PMID 32514250, 2020). "Following exposure to oxidizing saline solutions, we identified an upregulation of key ICD-markers, such as calreticulin (CRT), heat shock protein 70 (HSP70), and high-mobility-group-protein B1 (HMGB1) on the cell surface of CT26 colon-cancer cells using flow cytometry." (PMID 30679720, 2019). "lncRNA MALAT1 was upregulated in colon cancer tissues and may mediate HMGB1 by sponging miR-129-5p in colon cancer." (PMID 30984308, 2019). "Guido Kroemer’s team showed that a continuous exposure to oxaliplatin (from 15 to 300 μM, depending on the cell type) induces CRT exposure, ATP and HMGB1 release by different types of cancer cells, such as murine colon cancer (CT26), fibrosarcoma (MCA205) or human bone osteosarcoma (U2OS)." (PMID 31861811, 2019). "An increased of colon HMGB1 by dietary n-6 PUFA was observed in rats with colon cancer." (PMID 29670469, 2018). "Indeed, isotope experiments revealed that upon HMGB1 treatment colon cancer cells were forced to switch to anaerobic glycolysis (breakdown of glucose to lactate)." (PMID 27652323, 2016). "The potential of anti-HMGB1 to inhibit colon cancer development was also recently demonstrated." (PMID 23766911, 2013). "We have analyzed the colon cancer patient survival according to the serum HMGB1 level." (PMID 22496788, 2012). "We observed diverse ranges of HMGB1 secretion levels in the 10 colon cancer cell lines." (PMID 22496788, 2012). "Additionally, the higher level of HMGB1 detected in DCs existed in the metastatic lymph nodes of colon cancer patients." (PMID 20846416, 2010). "Since the memory T cells residing in colon cancers result from an acute immunologic response, this study further examined whether HMGB1 was involved in this process." (PMID 20846416, 2010). "More importantly, the expression of HMGB1 was observed in both the nucleus and the cytoplasm (co-expression pattern) in a subset of colon cancer tissues, whereas nuclear-only expression of HMGB1 (nuclear expression pattern) existed in most of the cancer tissues and normal mucosa." (PMID 20846416, 2010). "The co-expression of nuclear and cytoplasmic HMGB1 might be used as a marker for poor survival in patients with local advanced colon cancer." (PMID 20846416, 2010). "To determine whether the in vivo growth inhibition found in HMGB1-knockout clones was a general phenomenon caused by HMGB1 knockout, we established two HMGB1-knockout clones (3H6, 9D4) from CT26 colon tumor cells and compared their in vivo tumor growth in BALB/c mice with that of WT CT26 cells." (PMID 35150340, 2022). "HMGB1 inhibitor glycyrrhizin might be a promising drug in colon cancer cachexia." (PMID 34867338, 2021). "It was reported that HMGB1 released from necrotic cancer cells could enhance regrowth and metastasis of remnant colon cancer cells.Our results demonstrated that the level of HMGB1 was significantly elevated in both the cancer-cell cultured medium in vitro and the mice model following radiotherapy." (PMID 29615080, 2018). "As a main source of HMGB1 in vivo are epithelial cells, we performed these experiments on two other cell lines, the human intestinal colorectal adenocarcinoma cell line, Caco2, and the human colon carcinoma cell line HT29, in addition to the macrophage RAW 264.7." (PMID 23840500, 2013). "This study examined whether high-mobility group box 1 (HMGB1), a damage-associated molecular pattern (DAMP) molecule, is involved in the infiltration of T cells and disease progression in locally advanced colon cancer." (PMID 20846416, 2010).
colon carcinoma (continued). "Therefore, HMGB1-releasing colon cancer cells might promote effective angiogenesis and immune escape." (PMID 20846416, 2010). "High Mobility Group Box 1 (HMGB1) inhibits DC apoptosis via the JNK-autophagy axis, contributing to colon cancer cell immune evasion." (PMID 41246345, 2025). "In the colon cancer cell line LoVo, translationally controlled tumor protein (TCTP) upregulates the expression and secretion of HMGB1." (PMID 38529373, 2024). "Bleomycin, a Streptomyces verticillus-derived antibiotic, induces HMGB1, CALR, and IFNG expression in colon cancer cells." (PMID 39759512, 2024). "Experimental evidence suggests that the HMGB1/RAGE axis mediates the NF-kB signaling pathway, promoting the invasion of LoVo cells in vitro and the metastasis of colon cancer in vivo." (PMID 38529373, 2024). "There is a strong correlation between upregulation of the apoptosis repressing HMGB1 and c-IAP2 proteins in the pathogenesis of colon carcinoma." (PMID 34194625, 2021). "These researchers also reported that apoptosis was induced by transfection of BAK into the RKO colon cancer cell line and the human and mouse kidney cell lines (203T and NRK1), but that cotransfection of BAK with HMGB1 significantly inhibited apoptosis." (PMID 34267603, 2021). "And then correlation analysis showed that HMGB1 was positively correlated with GPX4 and p-p65, providing the therapeutic target for colon cancer." (PMID 32514250, 2020). "Subsequently, by utilizing 50 pairs of colon tumor tissues, we analyzed the expression and correlation about HMGB1, GPX4 and p-p65, and then evaluated their correlation in colon cancer." (PMID 32514250, 2020). "The present study showed HMGB1 expression were positively correlated with GPX4 and p-p65, these clinical findings suggest the therapeutic targets for colon cancer." (PMID 32514250, 2020). "Above results have proved the connection between HMGB1, GPX4 and p-p65 in SW480 and HCT116 cancer cells, we thereby explored the HMGB1, GPX4 and p-p65 correlation in colon cancer tissues." (PMID 32514250, 2020). "Pull-down, CoIP and immunohistochemistry assays were performed to further investigate the molecular mechanisms of HMGB1 and GPX4 in colon cancer." (PMID 32514250, 2020). "In conclusion, our results provided the evidences showing that acetylated HMGB1 can interact with GPX4, leading to oxidative stress and inflammation via NF-kB in colon cancer cells." (PMID 32514250, 2020). "Other studies showed that an increased MALAT1 expression promotes the proliferation of colon cancer cells, although by regulating other targets such as SOX9 and miR-129-5p/HMGB1 axis." (PMID 31733641, 2020). "Collectively, our findings first demonstrate that acetylated HMGB1 can interact with GPX4, leading to inflammation, and providing therapeutic strategies targeting HMGB1 and GPX4 for colon cancer." (PMID 32514250, 2020). "To further investigate the clinical relevance of HMGB1, we analyzed HMGB1 staining in primary colon tumor samples of 73 patients from TMA and found that high HMGB1 expression was positively correlated with tumor grade (p = 0.042)." (PMID 29844348, 2018). "This study observed that the co-expression of HMGB1 in the nuclear and cytoplasm was associated with poorer prognoses and lower infiltration of CD45RO+ cells, suggesting that spontaneous release and damage-induced release of HMGB1 might act differently in the progression of colon cancer." (PMID 20846416, 2010). "We examined the differentially expressed proteins by proteomic analysis and the CAC model of colon cancer in transgenic mice with intestinal epithelial overexpression of MSI2 was established, MSI2 was found to increase the expression of HMGB1 in vitro and in vivo." (PMID 38347600, 2024). "In addition, the protein levels of MSI2 and HMGB1 were increased in primary CRC specimens compared with normal adjacent tissues in our clinical CRC specimens and CPTAC Colon cancer dataset." (PMID 38347600, 2024).
colon carcinoma (continued). "Nevertheless, the detailed molecular mechanism of HMGB1-mediated CTSL-lysosome function in colon cancer therapy and platinum drugs has not been clearly defined." (PMID 37537587, 2023). "In colon cancer cells, HMGB1 binds with many isoforms of PKC, including PKCδ, ζ, ι, and λ, in which PKCδ mainly binds with nuclear HMGB1, while others predominantly bind to cytoplasmic HMGB1." (PMID 35632744, 2022). "We collected serum of colon cancer patients and found that HMGB1 was remarkably increased in cachexia patients than non-cachexia." (PMID 34867338, 2021). "HMGB1 is a transcription factor, which, along with amphoterin, effectively binds to RAGEs to promote the cancer cell proliferation, invasion, and VEGF production in colon cancer cells." (PMID 33466626, 2021). "In addition, our in vitro experiments demonstrated that HMGB1 induced proliferation and PCNA expression in CT26 colon cancer cells through the ERK1/2 pathway." (PMID 33160389, 2020). "In this study, our immunoprecipitation results showed that HMGB1 can interact with GPX4 in both colon cancer cells, thus leading to ROS accumulation and inflammation stimulated by LPS, identifying the novel mechanism for colon cancer therapy." (PMID 32514250, 2020). "The up-regulation of the lncRNA metastasis associated lung adenocarcinoma transcript 1 (MALAT1) mediates high mobility group box 1 (HMGB1) expression in colon cancer via competing with miR-129-5p, and the MALAT1/miR-129-5p/HMGB1 axis serves as a key prognostic marker in the development of the tumor." (PMID 32117736, 2020). "To determine whether HPA3P was able to induce the release of high mobility group protein B1 (HMGB1), an indicator of necrosis, in colon cancer cell lines, we performed western blot analysis in cell culture media." (PMID 29487701, 2018). "RB-treated colon cancer cells expressed distinct hallmarks of immunogenic cell death (ICD), including enhanced expression of calreticulin and heat-shock protein 90 on the cell surface, a decrease in intracellular ATP, and the release of HMGB1." (PMID 28151483, 2017). "In colon carcinoma cell lines, administration of the HDACi Vorinostat promoted tumor cell engulfment by dendritic cells and facilitated the expression of surface CRT and the release of HMGB1 and ATP." (PMID 27854240, 2016). "Likewise, the DNA-damaging agent, bleomycin, triggers ICD in colon carcinoma via ER stress, autophagy, redistribution of CRT/ERp57, ATP secretion, HMGB1 release, CD8+ T lymphocyte activation and IFNγ production." (PMID 27854240, 2016). "Hence, oHSV-1 expressing the HMGB1 protein (HSV-HMGB1) has shown enhanced cytotoxicity in normoxia but, paradoxically, increased colon cancer cell viability in hypoxia by inducing autophagy rather than apoptosis." (PMID 40507337, 2025). "We compared serum HMGB1 level in cachexia and non-cachexia colon cancer patients." (PMID 34867338, 2021). "The high-mobility group box-1 (HMGB1) and glutathione peroxidase 4 (GPX4) are responsible for inflammation, but the relationship between HMGB1 and GPX4 remains unknown about inflammation in colon cancer." (PMID 32514250, 2020). "In line with this, TCTP overexpression on colon cancer cell lines resulted in the release of HMGB1 from the nucleus to the cytoplasm and into the extracellular space led to activation of NF-κB through the RAGE/TLR4/HMGB1 mediation, which simplified CRC cell invasion." (PMID 33117687, 2020). "However, in the same conditions, neither HMGB1-fl nor HMGB1-ΔC could modulate Δψm in normal fibroblastic C19 cells or in the two colon carcinoma cell lines HT-29 and HCT-116." (PMID 35887213, 2022). "Furthermore, a HMGB1-dependent TLR-4/MyD88 pathway induces MAPK and Akt signaling chains, which end in inflammatory response and are also part of growth signaling in malignant cells, e.g., the phophatidylinositol 3 (PIP3)/Akt pathway is activated by HMGB1 in colon cancer cells." (PMID 26854151, 2015).